MMP3 (matrix metallopeptidase 3)
Diseases named in the same sentence as MMP3 in open-access papers (continued):
Sharing a sentence is not in itself a finding about the gene and the disease.
colitis (27 papers, 2013 to 2025). Inflammation of the colon. "uPA-mediated signaling (Timp1-, Mmp3-, Mmp9-centered sub-networks) controls macrophage phagocytosis in intestinal inflammation, and uPA receptor deficiency leads to marked aggravation of experimental colitis in mice." (PMID 36901742, 2023). "Since excessive collagen deposition may lead to the development of intestinal fibrosis, FRB seemingly reduced the risk of fibrosis due to DSS-induced colitis, by reducing the mRNA expression of Col1a1 and Col1a2 and increasing the level of Mmp3." (PMID 34070845, 2021). "Our findings corroborate that MMP10 and MMP3, regulated by IL-17 and involved in the inflammation-cancer relationship, become upregulated, enhancing IL-17 signal transduction and the release of inflammatory mediators, thus facilitating the development of colitis-associated colorectal cancer." (PMID 40595862, 2025). "To confirm the finding, we further analyzed the mRNA expression levels of Hdac11 and Mmp3 in the same mouse model (including colitis, CAC and normal colon tissues)." (PMID 35399729, 2022). "As expected, mice with acute DSS-induced colitis had significantly increased expression of Mmp3, Mmp8 and Mmp9 compared to control mice." (PMID 28561062, 2017). "It has been demonstrated that 5-HT exacerbated DSS-induced colitis by upregulating MMP-3 and MMP-9 expression in mice." (PMID 28694565, 2017). "In experimental colitis of animal or human gut explant models, MMP-3, -7, -9, -12 and TIMP-1 expression was elevated, and several MMP inhibitors significantly reduced tissue injury and inflammation." (PMID 27455234, 2016). "Our results support the notion that 5-HT exacerbates DSS-induced colitis by enhancing the production of MMP-3 and MMP-9." (PMID 27478308, 2016). "Orally administered docosahexaenoic acid had comparable efficacy to sulfasalazine in DSS induced colitis but with stronger inhibition of MMP-3, -10, and -13." (PMID 25948887, 2015). "Using the same mouse model, we further assessed the mRNA expression levels of Mmp3, Mmp10, and Mmp13 using quantitative real-time PCR (qPCR) of samples of mouse colitis tissue as well as CAC and normal colon tissues." (PMID 25742789, 2015). "Inhibition of the TWEAK pathway resulted in reduced severity of TNBS induced colitis in mice resulting in reduced expression of MMP-3, -9, -10, -12, and -13 along with other inflammatory mediators." (PMID 25948887, 2015). "Unlike BALB/c mice, both B6 wt and C3ar-/- mice showed substantial upregulation of MMP-3 mRNA after DSS-induced colitis." (PMID 23638016, 2013). "Likewise, IBD-related inflammation is associated with increased expression of MMPs, and studies in DSS model of colitis specifically reported exaggerated expression of MMP-3 and MMP-9." (PMID 40839695, 2025). "MMP3 inhibition improves the therapeutic effectiveness of IFX in colitis." (PMID 39782690, 2025). "These symbionts were exclusively enriched in the control group in our study, where they exhibited strong negative correlations with pro-inflammatory cytokines (IL-6, TNF-α) and inflammation-related genes (Lcn2, Mmp3), suggesting their protective role in mitigating colitis severity." (PMID 40356657, 2025). "However, the expression of MMP3 in mice with DSS-induced colitis was markedly upregulated following ME treatment." (PMID 34456904, 2021). "A previous study highlighted the protective effects of intraperitoneally administered pentoxifylline—a xanthine alkaloid derived from the seeds of the cacao tree (Theobroma cacao)—on TNBS colitis in rats through limiting TGFβ1 accumulation and MMP3 and MMP9 activation." (PMID 32855621, 2020). "Moreover, the levels of Mmp3, Mmp10, and Mmp13 proteins were also upregulated as determined with immunohistochemistry and western blotting of mouse colitis tissues and CAC tissues compared with normal colon tissues." (PMID 25742789, 2015).
colitis (continued). "Interestingly, the silencing of Mmp3 by siRNA markedly ameliorated DSS-induced colitis in mice, whereas knockout of Mmp9 or its pharmacological inhibition surprisingly had no obvious effect on the progression of DSS- and TNBS-stimulated colitis in the murine model." (PMID 36901742, 2023). "It was also found that the elevated MMP3 and MMP9 induced by serotonine might be associated with the serotonine-exacerbated DSS-induced colitis of mice, and the increased circulating MMP3 and MMP9 had been considered as biomarkers of the clinical activity of IBD." (PMID 35493520, 2022). "In the present study, MMP-3 and MMP-2 were shown to be upregulated in our DSS-induced colitis model, consistent with earlier studies." (PMID 40862456, 2025). "Experimental studies showed that FC alleviated DSS-induced colitis symptoms, reduced inflammatory cytokines release, and suppressed the expression levels of IL1β, COX2, MMP3, IL-17 and RORγt in colon tissues." (PMID 37161415, 2023). "Native ChIP assay was used to assay the levels of histone H3K9 and H3K14 acetylation at the Mmp3 promoter in normal and inflammation colon tissues from the AOM/DSS-induced colitis mice model." (PMID 35399729, 2022). "Most MMPs, such as MMP-2, MMP-3, MMP-7, MMP-9, MMP-10, MMP-12, and MMP-13 are increased in colitis and CAC." (PMID 36776395, 2022). "Upregulation of several secreted MMPs has been reported in the colonic mucosa of dogs with colitis, including MMP-1, MMP-3, and MMP-13, as well as MMP-2 and MMP-9." (PMID 35751094, 2022). "5-HT exacerbated DSS-induced colitis, low-dose 5-HT induces both MMP-3 and MMP-9, and high-dose 5-HT only increased MMP-3 mRNA expression in mouse colon." (PMID 27478308, 2016). "Infiltrating macrophages were seen to be a major source of MMP-8, -9, and -10 in human IBD and a mouse model of colitis and isolated IgG plasma cells from IBD patients were shown to produce high and sustained amounts of MMP-3." (PMID 25948887, 2015). "Despite the extensive studies of MMPs as candidate marker genes of colitis and CAC, to the best of our knowledge, the complex evaluation of the expression of Mmp3, Mmp7, Mmp9, and Mmp13 in acutely inflamed, adenomatous, and adjacent colon tissues has not yet been reported." (PMID 36901742, 2023). "Finally, the expression of the revealed hub genes related to acute colitis (C3, Tyrobp, Mmp3, Mmp9, Timp1) and CAC (Timp1, Adam8, Mmp7, Mmp13) was validated by qRT-PCR in the colon tissue of mice with acute colitis and colitis-driven adenomas." (PMID 36901742, 2023). "In a recent study highlighting the applicability of big data methods to such questions, investigators used a transcriptomic approach to find thatMmp9 and Mmp3 were overexpressed in colitis, but not in CAC." (PMID 38288108, 2023). "Inhibited TNF-α, iNOS, MMP-3, MMP-9 mRNA Expressions in colonic tissue of a colitis model." (PMID 35208860, 2022). "Apigenin also reduced levels of matrix metalloproteinase (MMP-3), which aids in extracellular remodeling, contributing to colonic inflammation, thereby showing protective effects in a murine DSS (dextran sulphate sodium) colitis model." (PMID 30764536, 2019). "5-HT induced MMP-3 and MMP-9 expression in mouse colon; these elevated MMPs may contribute to DSS-induced colitis." (PMID 27478308, 2016). "For example, inhibition of Notch signalling reduces MMP-3 and -9 expression in DSS induced colitis." (PMID 25948887, 2015). "Additional studies using in vivo models of colitis and CAC found that the expression signature of colitis (i.e., Mmp3 and Mmp9) versus that of CAC (i.e., Mmp7 and Mmp13) could predict the development of CAC in mice with dextran sulfate sodium (DSS)-induced colitis." (PMID 38288108, 2023).
colitis (continued). "In line with the results of network pharmacology approach, in vivo studies confirmed that FC alleviated DSS-induced colitis, reduced systemic inflammatory response, and diminished the expression of IL-17 signaling pathway mediators, IL-17A, RORγt, and tissue remodeling factors MMP1, MMP3 and MMP9." (PMID 37161415, 2023).
gastric cancer (27 papers, 2010 to 2024). A primary or metastatic malignant neoplasm involving the stomach. "All stromelysins (MMP-3, -10, and -11) have been reported to be upregulated in H. pylori infected gastric epithelial cells or H. pylori associated gastric cancer." (PMID 28398251, 2017). "For example, in eastern India, the MMP3 −709GG genotype conferred a risk for gastric cancer development." (PMID 23483952, 2013). "Additionally, expression of ASPN, which encodes an extracellular substrate in gastric cancer, and other inflammatory response genes (Mmp‐1, Mmp‐3) was increased in both CEFs and CAFs (green box)." (PMID 34379869, 2022). "Key lncRNA LINC02086 was experimentally verified to enhance proliferation and migration of gastric cancer cells by competitively binding to miR-93a-5p with MMP3." (PMID 38370380, 2024). "In gastric cancer cells, H. pylori–induced expression of MMP-3 and MMP-7 led to the downregulation of E-cadherin and accelerated cellular migration and invasion." (PMID 35163805, 2022). "H.pylori infection can reduce the function of E-cadherin by activating the matrix MMP-3 and -7, and induce the migration and invasion of gastric cancer cells." (PMID 34422902, 2021). "The prominent role of TIMP-3 in regulating proteolysis in vivo is highlighted by the observation, that expression levels of TIMP-3 decline while MMP-3 levels increasing during progression of gastric cancer." (PMID 28398251, 2017). "Though MMP-7 increases drastically in gastric cancer, it is of low prognostic value as marker, unless combined with MMP-3." (PMID 28398251, 2017). "In fact, the expression of MMP2, 7, and 9 is significantly elevated in gastric cancer tissues, and the silencing of MMP3 expression in gastric cancer cells decreased GA invasiveness." (PMID 29285307, 2017). "Berberine may inhibit cell migration by downregulating matrix metalloproteinase-3 (MMP-3) in gastric carcinoma cells, thereby exhibiting anti-metastatic activity." (PMID 32934709, 2020). "Since MMP-3 and -9 plays a pivotal role in gastric ECM degradation during Hp induced pathogenesis, and are associated with various carcinomas including gastric cancer, attenuation of their increased secretion and synthesis is critical for restoration of the gastric damage caused by Hp infection." (PMID 21283694, 2011). "For example, in gastric cancer, the MMP1 and MMP2 increased expression is related to the loss of E-cadherin expression, thereby, leading cancer proferliation and metastasis.MMP-3 and MMP-7 have association with the development of Helicobacter pylori-related gastric cancer." (PMID 34422902, 2021). "In gastric cancer cell (AGS) models, overexpression of MEG3 inhibited epithelial-mesenchymal transition (EMT) by decreasing MMP-3 and MMP-9 levels and thereby inhibiting cell migration." (PMID 36968595, 2023). "It was reported that the expression level of MMP-3, known as inducers of EMT, was negatively correlated with gastric cancer development." (PMID 33167519, 2020). "Next, the results of western blot indicated that peritoneal mesothelial cells significantly increased the protein expressions of MMP3, MMP9 and PCNA in metastatic gastric cancer cells, especially peritoneal metastatic gastric cancer cells." (PMID 32139657, 2020). "MMP-3 levels increase with tumor progression and elevated serum levels provide, in combination with MMP-7, a marker for poor prognosis in gastric cancer." (PMID 28398251, 2017). "Once H.Pylori has infected the stomach, it can stimulate the secretion of MMP-1, MMP-2, MMP-3 and TIMP-3 from gastric cancer cell, and finally prompt and speed up the progress invasion and metastasis of gastric cancer." (PMID 20637122, 2010). "The key targets of Zuojin pill MMP1, MMP3, and MMP9 play a therapeutic role in gastric cancer." (PMID 39086391, 2024). "In addition, increased levels of MMP-3, MMP-7 and MMP-11 in serum reflected an advanced stage of gastric cancer and also predicted shorter survival." (PMID 35163805, 2022).
gastric cancer (continued). "Thus, concomitantly increased serum levels of MMP-3 and MMP-7 seem to be more relevant for gastric dysplasia and gastric cancer." (PMID 35163805, 2022). "Furthermore, MMP-3 and MMP-7 were strongly elevated in the serum of patients with H. pylori–positive gastric cancer in comparison to the both gastritis groups." (PMID 35163805, 2022). "Metastatic gastric cancer cell supernatant treatment significantly downregulated E-cadherin expression in peritoneal mesothelial cells, while it notably upregulated N-cadherin, α-SMA, Snail, Twist, Slug, Cyclin D1, MMP3 and MMP9 expression." (PMID 32139657, 2020). "IL-33 promotes the production of IL-6 and MMP-3 by the ERK1/2 signaling pathway and enhances tumor invasion and escape ability in human gastric cancer (GC) cell lines." (PMID 36291105, 2022). "Likewise, in gastric cancer cells (SGC7901 and AGS lines), BBR treatment suppressed cell proliferation, induced cell cycle arrest, and attenuated invasion via the down-regulation of C-myc, cyclin-D1, and MMP-3 expressions, respectively." (PMID 34885950, 2021). "Finally, great of relevance, we found an upregulation of Matrix Metalloproteinase family (MMP1, MMP3, MMP10, MMP12), that are overexpressed in gastric cancer as a result of NF-Kb activation thus promoting migration and invasion, and are associated with poor prognosis." (PMID 34012923, 2021). "The enzymatic activities of MMP2 and MMP3 increased (MMP2 rs2285053 CC: 888.60 vs. CT: 392.00, p <0.0001; MMP3 rs679620 AA: 131.10 vs. GG: 107.74, p=0.015), whereas those of MMP8 decreased (MMP8 rs1940475 TT: 133.78 vs. CC: 147.54, p=0.011) in gastric cancer tissues." (PMID 29285307, 2017). "In the ceRNA network, MMP3 and LINC02086 could competitively bind miR-93-5p, as directly confirmed by our dual luciferase reporter assay in vitro, and in the LINC02086 knock down gastric cancer cells, MMP3 was accordingly down-regulated in both mRNA and protein levels." (PMID 38370380, 2024). "This revealed that the selected 36 out 37 targets (expression data for MMP3 was not available) were differentially modulated among tumor and normal tissues derived from the cholangiocarcinoma patients, again consistently to what observed in the gastric cancer specimens." (PMID 28199974, 2017).
ischemic stroke (25 papers, 2011 to 2025). A stroke disorder caused by obstruction of blood flow to the brain, due to thrombotic (local blood clot formation) or embolic (due to a blood clot or other material traveling from another site) event. "In 510 ischaemic stroke patients, MMP-3 was associated with IADE, suggesting a significance for MMPs in the formation of intracerebral dilative arteriopathy." (PMID 38019295, 2024). "MMP3 has been associated with vascular risk and can predict the risk of ischemic stroke and myocardial infarction." (PMID 30911000, 2019). "MMP-9 and MMP-3 have been implicated in neurovascular injury and apoptotic cell death in ischemic stroke, in both humans and rodent models." (PMID 26648273, 2015). "The MMP3 promoter polymorphism and expression levels of circulating MMP3 in patients are associated with acute myocardial infarction, left ventricle dysfunction, ischemic stroke, hemorrhagic stroke, and coronary syndrome." (PMID 32330120, 2020). "Similarly, the association between the MMP3 rs3025058 polymorphism and disease risk has been widely investigated for conditions such as ischemic stroke, coronary disease, chronic obstructive pulmonary disease and abdominal aortic aneurysm." (PMID 31652448, 2019). "Findings from our current study indicate that EP1 blockade could represent a novel alternative strategy to protect the BBB from MMP-9 and MMP-3-associated breakdown following ischemic stroke." (PMID 26648273, 2015). "Further analysis of differentially expressed genes (DEGs) between MMP-3 KO brains and WT brains was conducted to better understand the molecular mechanisms through which MMP-3 inhibition reduced tissue loss from ischemic stroke." (PMID 39000490, 2024). "In conclusion, genetic deletion of MMP-3 reduced brain infarct volume in our mouse model of ischemic stroke." (PMID 39000490, 2024). "In rtPA-administered ischemic stroke patients, Gołąb and his coworkers revealed that plasmin, which is known to be activated by rtPA, increases MMP-3 activity and influences the subsequent activation of MMP-9." (PMID 35163322, 2022). "Combined laser microdissection and protein array studies showed significant upregulation of MMP-3 in the human ischemic stroke brain, along with MMP-9." (PMID 34299322, 2021). "Our data show for the first time that pharmacological activation of EP4 with L-902,688 is neuroprotective in ischemic stroke by reducing MMP-3/-9 and BBB damage." (PMID 29527151, 2018). "MMP-9 and MMP-3 are key contributors to BBB disruption in the context of ischemic stroke since these proteases degrade the basal lamina and tight junction proteins essential to the barrier function of the neurovascular unit." (PMID 29527151, 2018). "However, there is controversy regarding the role of MMP-2 and MMP-3 after r-tPA treatment in ischemic stroke." (PMID 39273389, 2024). "Mechanistically, we identified that IFNβ attenuated delayed tPA-induced brain injury exacerbation, BBB disruption aggravation, and HT induction in ischemic stroke, and these protective effects were partly mediated through IFNβ-exerted suppression of MMP3 and MMP9 in the ischemic brain." (PMID 37063896, 2023). "Besides, we also noticed that GSS treatment reduced MMP-3 and MMP-9 mRNA and protein expression 41, provoking us to investigate the anti-inflammation effects and its underlying molecular mechanism of GSS in ischemic stroke." (PMID 33867831, 2021). "In the same study, another molecule, the MMP-3 haplotype 2, was associated with a reduced risk of myocardial infarction and increased risk of haemorrhagic stroke while showing no risk for ischaemic stroke." (PMID 35002488, 2021). "MMP-3 has been reported to promote hemorrhagic transformation after ischemic stroke." (PMID 29896414, 2018). "MMP-3 is produced by pericytes and ECs after ischemic stroke." (PMID 26834557, 2016). "MMP-9 and MMP-3 are two MMPs involved in acute injury in ischemic stroke." (PMID 26648273, 2015).